IL6 (interleukin 6)
Diseases named in the same sentence as IL6 in open-access papers (continued):
Sharing a sentence is not in itself a finding about the gene and the disease.
pneumonitis (37 papers, 2005 to 2025). An inflammatory process affecting the lung parenchyma. "Elevated expression levels of TNF-α and IL-6 have been associated with increased severity in radiation-induced toxicities such as pneumonitis and fibrosis." (PMID 40507362, 2025). "Based on this data, it seemed plausible that blocking the IL-6 pathway would help reduce the risk of recurrent pneumonitis with ICIs." (PMID 38414933, 2023). "The observed inflammatory changes were accompanied by an increase in cytokines, such as IL-1β and IL-6, as is observed in pneumonitis, which are associated with impaired lung function." (PMID 27144583, 2016). "One study showed an increased bacterial burden and mortality associated with pulmonary infection with the mouse pneumonitis strain (MoPn; now referred to as Chlamydia muridarum) in IL-6 -/- KO mice." (PMID 18628987, 2008). "This entails the development of predictive biomarkers, such as dynamic changes in circulating cytokines (e.g., T-cell recruiting CXCL9/10 versus pro-inflammatory IL-6/IL-8) and the peripheral T-cell repertoire diversity, to stratify patients for benefit and pneumonitis risk." (PMID 41438748, 2025). "Increased IL-6 has been reported for causing pneumonitis in post-thoracic radiotherapy patients." (PMID 28649248, 2017). "Importantly, high IL-6 or low ALB levels could be applied to improve risk stratification in pneumonitis." (PMID 34327140, 2021). "This observed difference was driven primarily by endocrine (n = 7) and other irAEs (n = 11) for IL-5; dermatologic (n = 5), enterocolitis (n = 6), and endocrine irAEs for IL-6; and pneumonitis (n = 5) for TNF-α (P < 0.05)." (PMID 39403935, 2024). "This was based on preliminary evidence on the role of IL-6 in mediating the irAEs, especially pneumonitis." (PMID 38414933, 2023). "IL-6 levels before, during and after thoracic radiotherapy were reported to be significantly higher in those who developed pneumonitis." (PMID 34830880, 2021). "T cell delayed over-responses can contribute to pneumonitis and delayed cytokine secretion with over-production of IL-6." (PMID 33335532, 2020). "In TLR2 -/- KO mice infected with mouse pneumonitis (MoPn), decreased fibrosis and inflammation with in oviducts and mesosalpinx correlated with abated IL-6 concentrations." (PMID 22894815, 2012). "SsRNA stimulation of human leukocytes induced cytokines/chemokines similar to those observed in murine SARS-CoV pneumonitis including IL-1α, IL-1β, IL-6, TNF, CXCL8 (IL-8), CCL2 (MCP-1), CCL3 (MIP-1α), and CCL4 (MIP-1β)." (PMID 23236475, 2012). "IL-6 levels before, during and after thoracic RT were significantly higher in those patients who developed pneumonitis in several reports." (PMID 19943923, 2009). "An increased frequency of ICOS+CD4+ T cells was a better predictor for pneumonitis development than those of CXCL13 or IL-6 levels, and combined assessment of both changes in ICOS+CD4+ T cells and CXCL13 levels had an even greater predictive value for later development of pneumonitis." (PMID 40198121, 2025). "However, clinical studies have shown that inhibition of IL-6 signaling can manage severe immune-related adverse events such as pneumonitis, serum sickness, and cerebritis." (PMID 35164829, 2022). "High IL-6 levels (OR: 5.23, 95% confidence interval [CI]: 1.15–23.86; p = 0.033), and low levels of ALB (OR: 0.16, 95% CI: 0.04–0.64; p = 0.009) measured at the time of CIP symptom onset were associated with severe pneumonitis." (PMID 34327140, 2021). "Furthermore, we have also shown elevated levels of interleukin-6 (IL-6) corresponding to elevated CRP in a patient with pneumonitis." (PMID 31277704, 2019).
pneumonitis (continued). "Anti-IL6 therapy has been hypothesised to be effective in patients with ICI-pneumonitis." (PMID 38414933, 2023). "Hyper-elevation of Interleukin1 (IL-1), Tumor necrosis factor-1alfa (TNF-1 alfa), and Interleukin 6 (IL-6) produced by inflammatory macrophage M1 may damage the lung alveoli leading to severe pneumonitis, decreased oxygenation, and potential death despite artificial ventilation." (PMID 32489696, 2020). "Several guidelines recommend immunomodulatory agents, such as TNF-α inhibitors, anti-IL-6, and intravenous immunoglobulin (IVIG), as second-line treatment for steroid-refractory ICI-pneumonitis." (PMID 36944820, 2023). "Cytokines such as IL-1α, IL-1β, IL-6, and TNF-α are produced in excess and potentiate pathological processes such as pneumonitis and vascular thrombosis." (PMID 35991665, 2022). "High levels of IL-6 and low concentrations of ALB at the time of initial onset of CIP symptoms were predictive of severe pneumonitis." (PMID 34327140, 2021). "The TNF-α inhibitor, infliximab, and the IL-6 inhibitor, tocilizumab, are used as second-line therapies in patients with steroid-refractory irAEs, including ICI-Pneumonitis." (PMID 34675810, 2021). "Cytokines released from damaged lung cells (such as IL-1, IL-6, or TNF-α) attract inflammatory cells to the alveoli and pulmonary interstitium, inducing the acute phase pneumonitis." (PMID 31858307, 2019). "The mRNAs detected were for cytokines involved in acute inflammation and the fibrosis of pneumonitis: TNF-α/β, IL-6, IFN-β/γ, IL-6, IL-10, IL-1α/β, IL12 and MIF." (PMID 16336675, 2005). "Certain markers of inflammation (i.e. Interleukin-6) rise in patients that go on to develop pneumonitis, however no study has evaluated a large panel of inflammatory markers in individual patients." (PMID 25573181, 2015).
subarachnoid hemorrhage (37 papers, 2012 to 2025). A serious neurological disorder characterized by intracranial hemorrhage into the subarachnoid space. "Apart from that, many serum inflammatory biomarkers, such as CRP and serum interleukin-6, were identified as risk factors for predicting an unfavorable prognosis in subarachnoid hemorrhage." (PMID 40951671, 2025). "In the case described, the patient’s history of a ruptured posterior communicating artery aneurysm and subarachnoid hemorrhage caused increased levels of IL-6 making him predisposed to an inflammatory response." (PMID 39429373, 2024). "Higher levels of IL-6 detected between 3 and 7 days after subarachnoid hemorrhage were associated with delayed ischemic neurological deficits and unfavorable outcome." (PMID 31701356, 2020). "One study also reported higher IL-4 concentrations in the cerebrospinal fluid of patients who developed delayed ischemia, while IL-6 levels in serum on day 3 after subarachnoid hemorrhage correlated with clinical status at diagnosis and at 6 months." (PMID 40362194, 2025). "It is known from studies conducted in patients with subarachnoid hemorrhage that IL-6 has an important role in evolving the vasospasm in cerebral vasculature." (PMID 39544563, 2024). "Several studies reported that the CSF levels of IL-6 were much higher than the serum levels in patients with subarachnoid hemorrhage, chronic inflammatory disease, seizures, and post-traumatic stress disorder." (PMID 35330399, 2022). "Fan and colleagues reported that treatment with mdivi-1 decreased brain expression of IL-1β, TNF-ɑ, and IL-6 24 h after subarachnoid hemorrhage injury in rats." (PMID 33612100, 2021). "Pro-inflammatory cytokines, such as IL-1β, IL-6, and tumor necrosis factor-α, which have been shown to be activated in POEMS syndrome, are reportedly associated with cerebral vasospasm after subarachnoid hemorrhage." (PMID 34167480, 2021). "A cytokine interleukin-6 (IL-6) was found to be a reliable marker for prediction of bacterial infection in adult neurosurgical patients with EVD after subarachnoid haemorrhage, when performed on daily basis." (PMID 31023301, 2019). "Interleukin-6 (IL-6), an inflammatory cytokine, plays important roles in cerebrospinal fluid (CSF) after subarachnoid hemorrhage (SAH)." (PMID 27576738, 2016). "A similar effect on vasospasm of IL-1 and IL-6 was suggested by a study of cerebral blood flow in subarachnoid haemorrhage where increased cerebral blood flow velocities were associated with significantly increased CSF concentrations of IL-1, IL-6, and TNF." (PMID 25610703, 2014). "IL-6 is a proinflammatory cytokine reported to play an important role in the induction of cerebral vasospasm after subarachnoid hemorrhage (SAH)." (PMID 25125049, 2014). "The effects of ROF on cerebral inflammation developing in the subarachnoid hemorrhage model in rats were investigated and it was shown that it significantly reduced neurological damage and inflammatory cytokines IL1β, IL-6, and TNFα levels and the number of apoptotic neurons." (PMID 36865049, 2023). "Moreover, a potential role for IL-6 in epileptogenesis has been reported in cases of subarachnoid hemorrhage, where IL-6 was significantly elevated in patients that developed seizures." (PMID 32552898, 2020). "However, the subarachnoid hemorrhage results in release of pro-inflammatory cytokines such as IL-1, IL-6, and TNF-α from microglia and macrophages, resulting in local and systemic inflammation." (PMID 32326289, 2020). "In addition prior reports show P2X7-mediated IL-6 release and early brain injury after subarachnoid hemorrhage to be dependent on the activation of p38-MAPK." (PMID 25938443, 2015). "Rn-C has also been shown to have antioxidant activities and can prevent interleukin-1b (IL-1b), interleukin-6 (IL-6), and tumor necrosis factor-alpha (TNF-α) mRNA expression in animals subjected to subarachnoid hemorrhage." (PMID 35631453, 2022).
subarachnoid hemorrhage (continued). "Supportively, one study showed that Mdivi-1 (1.2 mg/kg) injection after subarachnoid hemorrhage inactivated nuclear translocation of NF-κB and thereby reduced the levels of TNF-α, IL-6, and IL-1ß in ischemic-induced brain damage in MCAO rat models." (PMID 35002619, 2021). "In a model of subarachnoid hemorrhage in rats, a very recent study found that AE1-329, an EP4 receptor agonist, significantly reduced BBB damage, edema, and expression of IL-1β, IL-6, and TNF-α." (PMID 29527151, 2018). "Real-time PCR data demonstrated that baicalin attenuated increased proinflammatory cytokine (IL-1β, IL-6, and CXCL-3) production in subarachnoid hemorrhage mice." (PMID 28912935, 2017). "Changes in IL-6 serum concentration are not characteristic exclusively for ischemic infarcts and have been also found in the course of subarachnoid hemorrhage and hemorrhagic stroke." (PMID 31701356, 2020).
acute liver failure (36 papers, 2006 to 2026). Rapid deterioration of liver function causing encephalopathy and coagulopathy. "Inflammatory cytokines such as TNF-α, IL-1β and IL-6 are the key pathogenic factors of LPS/d-GalN-induced acute liver failure." (PMID 35645173, 2022). "In the context of acute liver failure, high levels of circulating IL-6 and TNFα are associated with impaired outcome in some studies, while in the hepatic compartment itself IL-6 seems to be protective as it downregulates TNFα-induced hepatic apoptosis." (PMID 34504196, 2021). "Further clinical research is needed to evaluate the potentialbenefits of using IL-5 and/or IL-6 as possible biomarkers for identifying patients witha higher risk of developing severe acute liver failure." (PMID 27812602, 2016). "Previously, it was demonstrated that serum S100B and IL-6 levels were associated with HE in pediatric patients suffering from acute liver failure, indicating that measuring these markers may be of benefit to the assessment of neurological injury, impacting clinical decisions." (PMID 36983411, 2023). "IL-6 was significantly elevated in direct co-cultures of rat hepatocytes treated with the serum of an acute liver failure patient and human orbital fat-derived stem cells and was the key factor mediating the protective effects of MSCs." (PMID 37894893, 2023). "In an in vitro model, rat hepatocytes treated with sera from animals given D-galactosamine to induce acute liver failure underwent massive cell death and began to express high levels of IL-6." (PMID 37894893, 2023). "In this study, SS pretreatment effectively reduced NO, TNF-α, IL-1β, and IL-6 secretion in paracetamol-induced acute liver failure." (PMID 34199606, 2021). "In conclusion, the current feasibility study demonstrated that UDCA reduced the expression of TNF-a and Il-6 during the priming phase of liver regeneration, in a setting of acute liver failure." (PMID 33489534, 2020). "Whereas TNF-α is most commonly viewed as a pro-inflammatory agent in acute liver failure, IL-6 can directly protect hepatocytes from oxidative stress after APAP toxicity, and both have long been known to stimulate liver regeneration." (PMID 32825435, 2020). "In a recent study, increased brain efflux of IL-1β, TNFα, and IL-6 was identified in patients with uncontrolled intracranial hypertension due to acute liver failure." (PMID 32178308, 2020). "Our study reveals the critical role of monocyte-derived IL-6 in initiating and accelerating acute liver failure and hUC-MSC treatment can disrupt the development of the inflammatory cascade by inhibiting monocyte activation." (PMID 30867056, 2019). "It is well recognized that IL-6 and IL-10 have an important role in improving recovery after acute liver failure." (PMID 28326105, 2017). "Elevations of the proinflammatory cytokines interleukin (IL)-1β, IL-6, and tumor necrosis factor alpha (TNFα) are observed in both patients and in rodent models of acute liver failure." (PMID 27561705, 2016). "We have previously shown that chemokine ligand 2 (CCL2) is one pathogenic chemotactic cytokine that is elevated in neurons during hepatic encephalopathy due to acute liver failure and contributes to both microglia activation and the elevation of IL-1β and IL-6." (PMID 27561705, 2016). "Indeed, tumor necrosis factor-α, interleukin (IL)-1β, and IL-6 levels were increased in patients with acute liver failure as well as in rodent models of acute liver failure, and are thought to contribute to cerebral edema and intracranial pressure." (PMID 25012628, 2014). "The PPARδ agonist GW501516 improves survival in a mouse model of acute liver failure induced by LPS/D-GalN, primarily by suppressing the expression of pro-inflammatory cytokines such as TNF-α, IL-6, and NOS2 in vivo." (PMID 39519830, 2024). "IL-6 is the main regulator in balancing Treg cells and Th17 cells, which are closely related to CHB, HBV-related chronic and acute liver failure (ACLF), and HCC." (PMID 37361218, 2023).
acute liver failure (continued). "Previous studies have shown that the proinflammatory cytokines such as IL-6 and MCP-1 as the primary mediators accelerated liver damage in LPS-induced acute liver failure in the early stage." (PMID 36558882, 2022). "In a previous study, MSCs reduced liver injury and lowered IL-1β, IL-6, and TNF-α levels in a lipopolysaccharide-induced acute liver failure rat model." (PMID 35765490, 2022). "CCL11 (Eotaxin) was selectively increased in biliary atresia patients, while IL-3, IL-6, CXCL8 (IL-8), IL-9, IL-16, MIF, CCL4 (MIP-1 β), and CXCL1 (GRO-α), were increased in both biliary atresia and acute liver failure." (PMID 30740106, 2019). "The study on madecassoside found that it could ameliorate drug-induced acute liver failure by reducing inflammation (TNF-α ↓, IL-1β ↓, IL-6 ↓, iNOS ↓, COX-2 ↓) and oxidative stress (SOD ↑, CAT ↑, GPx ↑, Nrf2 ↑, HO-1 ↑)." (PMID 33013406, 2020). "Elevated serum levels of several cytokines, including TNF-α, sTNF-αR1, sTNF-αR2, IL-2, IL-2R, IL-4, IL-6, IL-8, IL-10, and interferon-γ, have been described in patients with ACLF, whereas other studies reported normal TNF-α levels in patients with ACLF or acute liver failure." (PMID 17156425, 2006).
astrocytoma (36 papers, 1994 to 2025). "Latent infections of HHV-6 in astrocytoma cell lines have resulted in the production of IL-6, and a high level of IL-6 is associated with increased suicide risk." (PMID 37766304, 2023). "Constitutively active Gαq, Gαq/12, and Gαq/13 overexpressed in human astrocytoma cells increased agonist-activated thromboxane A2 receptor-mediated IL-6 production while mutated Gαq and Gαq/13 overexpression blocks IL-6 production." (PMID 26664886, 2015). "IL-6 gene amplification in patients distinguishes GBM from low-level astrocytoma and is associated with poor prognosis." (PMID 19055779, 2008). "EGCG impedes the release of vascular endothelial growth factors IL-6, and IL-8 in human astrocytoma (U373MG cells)." (PMID 35790919, 2022). "Activation of this receptor by serotonin in the U-373 MG astrocytoma cell line induces IL-6 secretion, facilitating tumor progression." (PMID 35455961, 2022). "Using primary human astrocytes and U-118 MG astrocytoma cells, they found that high glucose increased mRNA expression of IL-6 and secretion of both IL-6 and IL-8 by astrocytes." (PMID 34200240, 2021). "In astrocytoma cells, IL-1α contributes to the transcription and activation of IL-8 and IL-6, thereby inducing chronic inflammation." (PMID 33235296, 2020). "In one such study, it was reported that basal IL‐6 levels were higher in astrocytoma xenografts with resistance to selumetinib (a MEK1/MEK2 inhibitor) than in parental selumetinib‐sensitive astrocytoma xenografts." (PMID 30582770, 2019). "For instance, C3a and C5a signaling enhances IL-6 production in astrocytoma cells, and blocking C5aR signaling down regulated the expression of IL-6 in a mouse model of lung carcinogenesis." (PMID 31134065, 2019). "Consistent with our findings, LPS exposure induces release of IL-1β and IL-6 in U373-MG human astrocytoma cells." (PMID 28881826, 2017). "The selective CK2 inhibitor CX-4945 significantly reduced the IL-1β/TNF-α induced secretion of the inflammatory cytokines MCP-1 and IL-6 both in human primary astrocytes and U373 astrocytoma cells in a dose-dependent manner." (PMID 26732432, 2016). "Previous publications demonstrated that activation of β2-adrenergic receptors enhances TNF-α-induced expression of IL-6 in both rat astrocytes and the human 1321 N1 astrocytoma cell line." (PMID 24479486, 2014). "MAPKs have been reported to be involved in adenosine A2B receptor-mediated regulation of IL-6 gene expression in astrocytoma cells." (PMID 22894638, 2012). "We theorize that this increase in IL-6 may be mediated by PGE2 since PGE2 has been found to induce IL-6 synthesis in a human astrocytoma cell line, human synovial fibroblasts, cultured astrocytes, and a murine model of inflammation." (PMID 35844236, 2022). "Clinical effectiveness of NSAIDs in IL-6 producing paraganglioma may be explained by experiments using a human astrocytoma cell line that revealed that naproxen affects post-translational modification of IL-6 protein or secretory processes." (PMID 33715142, 2021). "1321N1 astrocytoma cells were incubated with α-syn to determine the effect on IL-6 secretion." (PMID 32911644, 2020). "Furthermore, human astrocytoma cells were challenged with 0, 1, 10, 100, or 500 ng/ml of IL-17 for 24 h, and then the production of pro-inflammatory cytokines IL-1β, IL-6 and TNF-α were determined by ELISA." (PMID 28281545, 2017). "Control human astrocytoma cell line U87 secretes interleukin-6 at the level 386 pg/ml." (PMID 25841889, 2015). "A further hypothetical correlation between the two tumor types is the commonly activated nuclear factor-κB (NF-κB) pathway and the excessive release of interleukin (IL)-6, which have been demonstrated to promote tumor cell proliferation and the invasion of astrocytoma and MM." (PMID 24137217, 2013).